RAF1 (Raf-1 proto-oncogene, serine/threonine kinase)
Diseases named in the same sentence as RAF1 in open-access papers (continued):
Sharing a sentence is not in itself a finding about the gene and the disease.
cardiac hypertrophy (16 papers, 2013 to 2024). "RAF kinases (ARAF/BRAF/RAF1) integrate signals into the extracellular signal-regulated kinase 1/2 cascade, a pathway implicated in cardiac hypertrophy, and activation of BRAF in cardiomyocytes promotes compensated hypertrophy." (PMID 36331065, 2022). "Because of the high probability of myocardial hypertrophy caused by RAF1 mutation, B-mode ultrasonography should be performed as soon as possible after discharge to prevent misdiagnosis and missed diagnosis of hypertrophic cardiomyopathy." (PMID 35953836, 2022). "RAF1 rs3729931 was found to be associated with cardiac hypertrophy in a GWAS conducted among patients from an Amish population." (PMID 30597917, 2018). "Patients with RAF1 mutations tend to have more pronounced cardiac hypertrophy." (PMID 39594917, 2024). "In addition, knockin mice expressing the Noonan syndrome-associated RAF-1 (L613V) mutation showed eccentric cardiac hypertrophy and heart failure following pressure overload." (PMID 31052420, 2019). "However, the child developed hypertrophic cardiomyopathy, which was consistent with Mussa A, who discovered the RAF1:c.770C > T (Ser257Leu) mutation, but the patient developed myocardial hypertrophy and pulmonary hypertension during the neonatal period, resulting in death during the neonatal period." (PMID 35953836, 2022). "In particular, RAF kinases (ARAF/BRAF/RAF1) have already been identified as key regulators during cardiac hypertrophy in mice." (PMID 38892401, 2024). "Gelb and Tartaglia summarize that Ras/MAPK pathways activated by either Raf1 or B-Raf are involved in cardiac hypertrophy." (PMID 29466442, 2018). "For instance, the Raf-1 has been verified as a key determinant of myocardial hypertrophy in mice following aortic banding." (PMID 27082116, 2016). "However, no effective treatment has been found for myocardial hypertrophy caused by RAF1, and its clinical study is currently underway." (PMID 35953836, 2022). "Nevertheless, future studies will be needed to determine the effect of TNF inhibition on all of the paracrine signalling molecules altered in RAF1-mutant ECs and to assess the dose-response relationship between TNF inhibition and cardiac hypertrophy." (PMID 28548091, 2017). "Moreover, the activation of PKC-β can activate Raf-1 and the MAPK signaling cascade in the cytoplasm, which in turn mediates cardiac hypertrophy." (PMID 34690749, 2021).
fibrosarcoma (16 papers, 2011 to 2026). A malignant mesenchymal fibroblastic neoplasm affecting the soft tissue and bone. "Mice treated with doxorubicin alone exhibited lower tumor levels of Ras, phosphorylated-rapidly accelerated fibrosarcoma (p-Raf1), mitogen‐activated protein kinase kinase (p-MEK), and extracellular signal‐regulated kinase (p-ERK) than did controls." (PMID 36483592, 2022). "Cleaved cFLIP then allows a more efficient recruitment of TRAF1/2, the 'receptor-interacting protein' (RIP1) and the the 'rapidly growing fibrosarcoma or rat fibrosarcoma-1' (Raf-1) protein to the cFLIP-caspase-8 heterodimer." (PMID 21477291, 2011).
hypertrophic cardiomyopathy (16 papers, 2016 to 2025). A condition in which the myocardium is hypertrophied without an obvious cause. "As expected, PTPN11 variants demonstrated a significant association with PVS and ASD (p < 0.05), while those involving RAF1 were preferentially associated with hypertrophic cardiomyopathy (HCM) (p < 0.0001)." (PMID 40332000, 2025). "Pathogenic variants in RAF1 are found in about 5–10% of individuals, frequently linked to hypertrophic cardiomyopathy." (PMID 40332000, 2025). "Differences in clinical severity also reflect the hierarchical positioning of proteins within the pathway; for instance, RAF1 variants preferentially activate cardiac-specific signaling pathways, explaining the high prevalence of hypertrophic cardiomyopathy." (PMID 40332000, 2025). "Other reported associations, such as hypertrophic cardiomyopathy with RAF1 mutations and ectodermal anomalies with HRAS mutations (Costello syndrome), were also partially recapitulated in our cohort, further validating established phenotypic correlations." (PMID 41292581, 2025). "The RAF1 gene mutations show low incidence, accounting for 5–10% of NS cases, with many patients presenting with hypertrophic cardiomyopathy as a specific cardiologic feature." (PMID 39336782, 2024). "Mutations in PTPN11 were most commonly associated with pulmonary valve stenosis (PVS), while RAF1 mutations were prevalent in patients with hypertrophic cardiomyopathy (HCM)." (PMID 39596663, 2024). "Studies on 3D bioartificial cardiac tissues reveal the impacts of hypertrophic cardiomyopathy-associated RAF1 mutations on sarcomere structure, contractile behavior, Ca2+ handling, and intracellular signaling." (PMID 37344639, 2023). "Distinct variants, including the recurrent Ser257Leu substitution in RAF1, are associated with severe hypertrophic cardiomyopathy (HCM)." (PMID 37344639, 2023). "Signs of hypertrophic cardiomyopathy (HCM) were found in 3 patients (9%): one of them presented an obstructive form with a RAF1 mutation, which is known for being associated with this feature." (PMID 36566191, 2022). "These preclinical results support the development of rigosertib for the treatment of RAF1‐associated hypertrophic cardiomyopathy in patients." (PMID 35266292, 2022). "More than 90% of NS patients with mutations in conserved region 2 of RAF1 suffer from severe hypertrophic cardiomyopathy, resulting from abnormal ERK5 and MEK1/2 signalling." (PMID 35953836, 2022). "Mutation in the RAF1 gene has been connected with a variety of maladies covering hypertrophic cardiomyopathy, mental retardation, short stature, and Noonan-like skin features associated with freckle syndrome (multiple freckles, nevi cafe-au-lait, multiple nevi)." (PMID 35953836, 2022). "Loss-of-function variants in LZTR1 likely remove a critical checkpoint in this pathway, contributing to a spectrum of features including mild dysmorphisms and cardiac anomalies, although with a reduced prevalence of hypertrophic cardiomyopathy compared to RAF1 or PTPN11." (PMID 40332000, 2025). "Notably, more than 90% of NS individuals with a RAF1 variant are affected by HCM, whereas the overall frequency of hypertrophic cardiomyopathy (HCM) in NS is only about 20%1,2." (PMID 37344639, 2023). "Notably, the mutation of RAF1, which is also an ASD-associated gene, is additionally associated with dilated cardiomyopathy and hypertrophic cardiomyopathy, whose two corresponding pathways were found to be enriched and merged into collection cardiac diseases from the pathway network." (PMID 27055244, 2016). "In hypertrophic cardiomyopathy (HCM), MYBPC3, MYH7, PRKAG2, RAF1, and RBM20 were prevalent." (PMID 41341110, 2025). "The RAF1 gene is located in the chromosome 3p25 region, and three species of RAF can activate the MEK-ERK cascade to produce RAS effects, which are manifested as prominent hypertrophic cardiomyopathy." (PMID 39726952, 2024).
LEOPARD syndrome (16 papers, 2011 to 2025). "RAF1 in particular has been recognized as a major effector whose gain-of-function mutations cause Noonan and LEOPARD syndromes, emphasizing the importance of the ERK pathway activation in developmental disorders." (PMID 33263009, 2020). "Altered RAF1 is associated with the development of Noonan and LEOPARD syndrome, AML, and pilocytic astrocytoma." (PMID 24827933, 2014). "This is also the case for 8/14 syndromic HCM (CACNA1C, FLNC, PRKAG2, PTPN11 (Noonan), PTPN11 (Noonan syndrome with multiple lentigines), RAF1, RIT1, TTR), 3/12 DCM (DES, TNNC1 and TNNT2), and 2/6 ARVC (JUP, TMEM43) gene-disease pairs." (PMID 37872640, 2023). "Seven genes (PTPN11, SOS1,KRAS, RAF1, BRAF,SHOC2 and MEK1, alias MAP2K1) have beencausally related to NS and closely related conditions (including LEOPARDsyndrome) and clinically related disorders (e.g. neurofibromatosis type 1)." (PMID 21526175, 2011). "No mutations onthe RAF1 gene were identified in negative cases ofPTPN11, SOS1, and KRAS.Patients #39 and #41 were posteriorly diagnosed with suffering from LEOPARDsyndrome, and in fact, they carried the characteristic mutations on genesPTPN11." (PMID 21526175, 2011).
cervical cancer (14 papers, 2014 to 2025). A primary or metastatic malignant neoplasm involving the cervix. "Wu and Zhou demonstrated that circAGFG1 facilitated the development of cervical cancer through targeting the miR-370-3p/RAF1 axis." (PMID 34013042, 2021). "In our research, circAGFG1, miR-370-3p and RAF1 constituted a ceRNA network to regulate cervical cancer cellular processes." (PMID 31703640, 2019). "In summary, this study revealed that circAGFG1 exerted oncogenic properties in cervical cancer by sponging miR-370-3p to upregulate RAF1." (PMID 31703640, 2019). "Our study showed that circAGFG1 promoted cervical cancer progression via miR-370-3p/RAF1/MEK/ERK signaling." (PMID 31703640, 2019). "rVP1 suppresses cervical cancer cell metastasis by decreasing membrane bound PIP3 leading to modulation of phospho-PHBT258 in the lipid rafts of the cervical cancer cells and inactivation of Raf-1/ERK." (PMID 25004182, 2014). "Similarly, miR-497 achieved its anti-tumor role by negative regulation of the MAPK/ERK signaling pathway via targeting RAF1 in cervical cancer." (PMID 39076089, 2024). "Several lines of evidence suggest that, in cervical cancer, the Ras/Raf1/MEK/ERK pathway, but not the JNK pathway or the p38 MAPK pathway, is the major regulator of cell proliferation." (PMID 26366416, 2015).
lung adenocarcinoma (14 papers, 2009 to 2026). A carcinoma that arises from the lung and is characterized by the presence of malignant glandular epithelial cells. "In support of this, ARAF dimers have been found to promote ERK signaling and cell cycle arrest in KRAS-mutated, RAF1-deficient lung adenocarcinoma cell lines." (PMID 37020037, 2023). "In lung adenocarcinomas with KRAS mutations, RAF1 ablation in tumors leads to significant regressions including some complete regressions." (PMID 38137485, 2023). "Thus, in agreement with results obtained in lung adenocarcinomas also with RAF1 kinase-dead reconstitution experiments, RAF1 kinase activity is dispensable for cell proliferation in CRC spheroids and organoids." (PMID 37020037, 2023). "Recent studies have highlighted kinase-independent roles of RAF1 in KRAS mutant lung adenocarcinoma that could either be anti-apoptotic or pro-proliferative." (PMID 37020037, 2023). "Our findings suggest thatDEGs encoding subunits of NADH, PRIM1, MCM3, MAPK1, STAT3, RAF1, and JAK1 might beassociated with the development of lung adenocarcinoma." (PMID 26840709, 2016). "In addition to impacting proliferation, RAF1 could exert anti-apoptotic functions, as observed in lung adenocarcinomas." (PMID 37020037, 2023). "Additionally, USP7 could regulate lung adenocarcinoma through USP7/Raf‐1/ERK1/2 axis." (PMID 39107958, 2024). "While RAS-driven melanoma and pancreatic ductal adenocarcinoma are highly dependent on RAF proteins to activate MEK/ERK, some other cancers require RAF1-specific functions that are MEK-independent, such as squamous cell carcinoma and lung adenocarcinoma." (PMID 37020037, 2023). "In summary, our results indicate that USP7 deubiquitinates Raf-1 and is a new regulator of the ERK1/2 signaling pathway in lung adenocarcinoma." (PMID 35948545, 2022). "Epicatechin and scopoletin induce apoptosis in leukemia (Jurkat, WEHI-3b) and lung adenocarcinoma (A549) through caspase-3/8 activation, G0/G1 arrest, and downregulation of tumor proliferation genes (EGFR, MDM2, RAF1, mTOR), while enhancing immune responses and reducing COX-2 expression." (PMID 41346617, 2025).
bladder cancer (13 papers, 2011 to 2025). "Similarly, a study in urinary bladder cancer linked deletions in an RAF1 region (3p25) with high tumor grades, advanced stages, and poor survival, which is consistent with our findings." (PMID 40362553, 2025). "RAF1 amplification defines a molecular subset of muscle-invasive bladder cancers with MAPK dependency, reinforcing therapeutic tractability of this axis in urothelial contexts." (PMID 41154349, 2025). "The evidence is also available that TP63+ bladder cancers, which all bear either HRAS or NRAS mutations, are particularly sensitive to RAF1 pathway inhibition." (PMID 39678505, 2024). "Bladder cancer was the most prevalent tumor having RAF1 amplifications with a frequency of 8.4% (11/131), which was slightly less frequent than a previous reported study and TCGA data." (PMID 38137485, 2023). "The KEGG bladder cancer pathway activation in poor prognosis CRCs was mostly due to increased expression of functional nodes HRAS/KRAS/NRAS, ARAF/BRAF/RAF1, MAPK1/MAPK3, and RPS6KA5." (PMID 36316649, 2022). "RAF1, a pro-growth protein kinase and HSP90 client, is overexpressed in 27% of bladder cancer cases." (PMID 30220976, 2018). "Five genes in this network (E2F1, E2F3, EGFR, RAF1, and RB1) significantly overlapped genes in the bladder cancer pathway from the Kyoto Encyclopedia of Genes and Genomes (KEGG) database (FDR q<0.01)." (PMID 29140994, 2017). "A total of nine chr3p25 and chr11p11 genes were functionally connected to genes in the KEGG bladder cancer pathway (E2F1, E2F3, EGFR, RAF1, RB1) or to other cancer-related genes (AKT2, PIK3CA, RB1, TRIO)." (PMID 29140994, 2017). "TTI1, RAF1 and YWHAZ combined are found to be overexpressed in 55% of all bladder cancer cases." (PMID 30220976, 2018). "Based on the pharmacological effects observed when blocking RAF1, it is suggested that quercetin and BDMC, derived from Xiaozheng decoction, may play a crucial role in inhibiting RAF1/MAPK-dependent malignant biological behavior in bladder cancer cells." (PMID 37608369, 2023).
acute myeloid leukemia (12 papers, 2011 to 2025). Acute myeloid leukemia (AML) is a group of neoplasms arising from precursor cells committed to the myeloid cell-line differentiation. "The genes contributing the most to the acute myeloid leukemia pathway (RAF1, RELA, and IKBKB) are related with NF-KB signaling, a process already known to also play a role in AD and PD." (PMID 33362460, 2020). "In cells of acute myeloid leukemia PTPIP51 is unable to interact with Raf-1 while phosphorylated at its tyrosine 176 residue." (PMID 24970130, 2012). "A 2018 study focusing on Wogonoside—a flavonoid extracted from Scutellaria baicalensis Georgi with antileukemic properties—reported that Wogonoside inactivates the NRAS/RAF1 signaling pathway by blocking NRAS palmitoylation in acute myeloid leukemia (AML) cells." (PMID 36018061, 2023). "In addition, exosomal circ_001264, derived from acute myeloid leukemia (AML) cells, activates the p38/STAT3 signaling axis by regulating RAF1 levels, followed by activating macrophage polarization toward the M2 type and elevating PD‐L1 expression." (PMID 39584047, 2024).
liver cancer (12 papers, 2016 to 2025). An epithelial or non-epithelial malignant neoplasm that arises from the liver. "In conclusion, we here propose a new diagnostic marker, the expression level of RAF1, to predict the early treatment effects of sorafenib on advanced liver cancer." (PMID 32190741, 2020). "The number of liver cancer progenitor cells (defined as CD44+/CD31− Ter119− CD45−) was significantly increased in RAF1-deficient organs." (PMID 28000790, 2016). "X‐inactive specific transcript (XIST), a long noncoding RNA highly expressed in liver cancer, promotes O‐GlcNAcylation of the RAF1 oncogene through the XIST/miR‐424‐5p/OGT axis." (PMID 41394960, 2025). "This modification inhibits ubiquitination‐mediated degradation of RAF1, enhances its stability and activity, and ultimately facilitates liver cancer proliferation and EMT." (PMID 41394960, 2025). "One of the recent studies has indicated its involvement in the progression of liver cancer by targeting the RAF1 and RAS-ERK signaling cascades." (PMID 38741808, 2024). "We plan to explore how PI3K, AKT, CDK1, CCND1 and RAF1 contribute to arecoline-induced liver cancer using a rat intrahepatic tumor transplantation model and siRNA interference." (PMID 35836300, 2022). "Our results indicate that by inducing the expression of let7i-3p, melatonin can potentially downregulate the expression of RAF1 and the activation of the oncogenic pathway downstream from RAF1, and thereby suppress the growth and metastasis of liver cancer cells." (PMID 30201903, 2018). "To investigate the role of hepatocyte RAF1 in an inflammatory environment similar to that of F/F mice, we concentrated on the Δp/np model and quantified the number of liver cancer progenitor cells 16 weeks after DEN treatment." (PMID 28000790, 2016). "The revelation of the crucial involvement of Raf1 and vascular endothelial growth factor (VEGF) mediated signaling pathways in the molecular pathogenesis of liver cancer provided an interesting theoretic basis for applying sorafenib drugs to liver cancer treatment." (PMID 36176764, 2022). "Hence, it is possible that MEK plays the same role in connecting Raf‐1 and p70S6K in NSCLC as that in liver cancer." (PMID 31541523, 2019).
ovarian carcinoma (12 papers, 2001 to 2022). A malignant neoplasm originating from the surface ovarian epithelium. "Furthermore, preclinical models have shown that in addition to BRAF mutations in low-grade tumors, Raf-1 isoform predominantly mediates ovarian cancer cell growth compared with Raf-A or B-Raf isoforms." (PMID 22235203, 2012). "Upregulated hsa_circ_0058514 is expressed in cervical cancer tissues and promotes RAF1 expression through the activation of miR-370-3p, which further regulates ovarian cancer progression via the RAF/MEK/ERK pathway." (PMID 36387225, 2022). "Although the total levels of Raf-1 remained unchanged, ovarian cancer cells transfected with either RASAL2-shRNA1 or RASAL2-shRNA2 showed a clear induction of Raf-1 phosphorylation compared with control cells." (PMID 25216515, 2014). "In our previous study, cisplatin increased Raf-1 and c-Fos expression in human ovarian carcinoma cells." (PMID 23817665, 2013). "There have also been reports demonstrating reduced survival in ovarian cancer patients with increased expression of Raf-1." (PMID 22235203, 2012). "In ovarian carcinoma cells, ISIS 5132 and ISIS 13650 induced 100% Raf-1 suppression and an 80% drop in cell proliferation." (PMID 22649602, 2009). "Interestingly, SNVs in PTEN (p.Cys124Ser and p.Ala126Thr) and PTPRT (p.Val1429Met), and one-base indels in RAF1 (p.Met350fs) and ARID1A (p.Arg1053fs) were shared by the endometrial and ovarian carcinomas but not found in the lung metastasis." (PMID 28103826, 2017).